CCL11 (C-C motif chemokine ligand 11)
Description:
Chemokine that plays a central role in both allergic and non-allergic inflammatory reactions by inducing the migration of different leukocyte types including eosinophils, basophils, macrophages and dendritic cells. Exerts its effects primarily by binding to the CCR3 receptor. Induces also chemotaxis of endothelial cells and promotes angiogenesis by activating the PI3K/Akt pathway.
Synonyms: SCYA11; eotaxin; MGC22554
Tractability: Antibody: a drug acting on it is in phase 2 or 3 trials; UniProt places it where antibodies can reach, with high confidence; its Gene Ontology location is reachable by antibodies, with high confidence; UniProt predicts a signal peptide or a membrane-spanning region.
Target class: Secreted protein
Safety:
Unwanted effects reported when the protein is acted on. In parentheses: how it was acted on, where the effect was seen, and who reports it.
insomnia (source: ClinPGx)
Gene: Protein-coding gene on chromosome 17 (34,285,742 to 34,288,334, forward strand). Ensembl gene ENSG00000172156.
Subcellular location: Secreted
Pathways (Reactome):
Immune System: Interleukin-4 and Interleukin-13 signaling
Signal Transduction: Chemokine receptors bind chemokines
Gene Ontology:
Molecular function: CCR3 chemokine receptor binding; chemokine activity; protein binding; protein dimerization activity; receptor ligand activity; CCR chemokine receptor binding
Biological process: cell chemotaxis; chemokine-mediated signaling pathway; cytoskeleton organization; eosinophil chemotaxis; positive regulation of actin filament polymerization; positive regulation of cell migration; positive regulation of endothelial cell proliferation; regulation of cell shape; antimicrobial humoral immune response mediated by antimicrobial peptide; cell adhesion; chemotaxis; inflammatory response; intracellular calcium ion homeostasis; learning or memory; negative regulation of neurogenesis; protein phosphorylation; response to radiation; response to virus; signal transduction; actin filament organization; chronic inflammatory response; ERK1 and ERK2 cascade; immune response; mast cell chemotaxis; positive regulation of angiogenesis; and 2 more
Cellular component: extracellular region
Genetic constraint (gnomAD): Loss-of-function variants: 5 observed, 5.47 expected, observed/expected ratio (o/e) 0.91, 90% interval 0.47 to 1.74. That is too few expected variants to judge how well the gene tolerates losing a copy. Missense variants: 107 observed, 90.49 expected, observed/expected ratio (o/e) 1.18, 90% interval 1.01 to 1.39. Synonymous variants: 51 observed, 33.18 expected, observed/expected ratio (o/e) 1.54, 90% interval 1.22 to 1.88.
Homologues: Orthologues: chimpanzee CCL11 (100% identical), macaque CCL11 (91% identical), rabbit CCL11 (77% identical), pig CCL11 (66% identical), guinea pig CCL11 (62% identical), rat Ccl11 (61% identical), mouse Ccl11 (59% identical), zebrafish cxcl32b.1 (32% identical). Paralogues in human: CCL2 (71% identical), CCL7 (70% identical), CCL8 (70% identical), CCL13 (65% identical), CCL4 (39% identical), CCL23 (38% identical), CCL21 (37% identical), CX3CL1 (37% identical), CCL15 (36% identical), CCL3L3 (36% identical), CCL4L2 (36% identical), CCL16 (35% identical), and 14 more.
Diseases named in the same sentence as CCL11 in open-access papers:
CCL11 is named in the same sentence as 293 diseases in open-access papers, as found by Europe PMC text mining. Sharing a sentence is not in itself a finding about the gene and the disease. The quoted sentences say what the papers report.
asthma (128 papers, 2007 to 2025). "Studies have shown that the CCL11 rs2302009 (A>G) variant is linked to an increased risk of asthma, particularly in individuals carrying the G allele, which causes a threonine-to-alanine substitution at position 23 in the CCL11 protein." (PMID 41149648, 2025). "Increased circulating CCL11 was implicated in several auto-immune and allergic diseases, including systemic lupus erythematosus, asthma, and multiple sclerosis." (PMID 38601164, 2024). "CCL11 is known to play a role in eosinophilic and basophilic activities, often linked to inflammatory allergic reactions such as asthma, atopic dermatitis, and inflammatory bowel disease." (PMID 37833765, 2023). "Eotaxin/CCL11 is a potent eosinophil chemoattractant, implicated in various eosinophil-related pathogenic processes such as asthma and airway inflammation." (PMID 31847862, 2019). "The adjusted ORs (95%CI) of association between IL-17A, IL-9, adipsin and CCL11 expressions and adult asthma were 3.08 (1.91, 4.97), 1.93 (1.41, 2.64), 10.02 (6.99, 14.37) and 3.29 (2.36, 4.59), respectively (all Ptrend < 0.0001)." (PMID 29138487, 2017). "CCL11 is also a potential diagnostic marker for asthma since it is significantly increased in serum of asthmatic patients." (PMID 29272313, 2017). "Our results suggested that elevated IL-17A and IL-9 expressions and decreased levels of adipsin and CCL11 were positively associated with adult asthma." (PMID 29138487, 2017). "In conclusion, we found that elevated plasma IL-17A and IL-9 levels and decreased plasma expressions of adipsin and CCL11 were positively associated with asthma risk in adults." (PMID 29138487, 2017). "Eotaxin-1 (CCL11) is a potent eosinophil chemoattractant that is normally associated with asthma, but is known to play a role in other mucosal diseases such as inflammatory bowel disease (see review)." (PMID 29065892, 2017). "CCL11 is traditionally associated with eosinophil recruitment and pro-inflammatory response, as seen in asthma or associated with highly destructive CNS lesions observed in neuromyelitis optica." (PMID 22815714, 2012). "An eosinophilic profile has also been reported in other chronic human liver diseases as well as asthma, atherosclerosis and pulmonary fibrosis, where the eosinophilic chemokine CCL11 (Eotaxin-1) has been implicated in pathogenesis." (PMID 21666794, 2011). "We show that CCL11 is required for recruitment of eosinophils, which have traditionally been considered end stage effector cells linked to parasitic infections and pathological type 2 disease states such as asthma and allergies, to STm-infected MLN." (PMID 39801515, 2025). "This substitution elevates plasma CCL11 levels, enhancing eosinophil recruitment to the airways, leading to increased allergic responses and intensified airway inflammation, which contribute to asthma susceptibility." (PMID 41149648, 2025). "Furthermore, the CCL11/CCR3 axis has been implicated in facilitating breast cancer lung metastasis under conditions of asthma-associated chronic inflammation, suggesting a potential link between allergic inflammation and cancer progression." (PMID 40429807, 2025). "CCL11, which is a key mediator in the selective recruitment of eosinophils to inflammatory sites during allergic responses, has been extensively investigated in asthma and related eosinophil-associated pathologies." (PMID 40429807, 2025). "In addition, we observed that decreased plasma CCL11 level was associated with increased risk of adult asthma." (PMID 29138487, 2017). "In addition, the abnormal IL-17A, adipsin and CCL11 levels were significantly associated with adult asthma." (PMID 29138487, 2017). "Increased production of CCL11 has been associated with allergic diseases such as asthma." (PMID 20169197, 2010).
asthma (continued). "In this model, the sub-epithelial TSLP/CCL11/eotaxin-1 responses of the asthmatic bronchial smooth muscle might underlie the presence of airway wall eosinophilc infilitration, one of the most striking features in the pathology of severe asthma." (PMID 25546419, 2014). "The effects of CCL11 are mediated by its binding to a G-protein-linked receptor known as a chemokine receptor, and it is able not only to decrease neurogenesis and cognitive performance but also, with other chemokines, to induce the migration of circulating fibrocytes in patients with severe asthma." (PMID 23988087, 2013). "Studies utilizing Ccl11−/− mice or treatments that inhibit CCL11 have demonstrated reduced inflammation in models of asthma and IBD39,40." (PMID 39801515, 2025). "Traditionally, CCL11 has been recognized for exacerbating Th2-type inflammation (e.g., asthma) via eosinophil recruitment, while genetic evidence from this study underscores its critical role in UC pathogenesis." (PMID 40958322, 2025). "SLITRK1 is associated with neurite development and synaptogenesis, and increased CCL11 expression can exacerbate asthma." (PMID 41472112, 2025). "In various inflammatory pathologies, including asthma, ulcerative colitis, Crohn’s disease, and drug-induced liver injury, CCL11 production is significantly upregulated in eosinophils, particularly in circulating eosinophils." (PMID 40429807, 2025). "The levels of CCL2, CCL3, and CCL5 in the BALF and CCL11 in plasma were significantly higher in asthma patients than in control subjects." (PMID 35743888, 2022). "For instance, TNFα-induced CCL11, CXCL8, or IL-6 release was less susceptible to suppression by dexamethasone in ASM cells obtained from patients with severe asthma when compared to those obtained from healthy subjects." (PMID 36012240, 2022). "The airway epithelium expresses CCL2, CCL3, CCL4, CCL5, CCL11, and CXCL5, which are associated with asthma." (PMID 35743888, 2022). "The levels of plasma CCL11 are significantly increased in atopic dermatitis patients and during asthma exacerbation compared to the stable phase of asthma." (PMID 33919759, 2021). "CCL11 is a key mediator in asthma and levels of this protein were measured by Elisa in lung tissue extracts." (PMID 33608009, 2021). "In line with this, is the observation that in the airways of asthma patients compared with healthy controls mRNA of CCL11 and CCL24 are increased at steady state." (PMID 33919759, 2021). "The results demonstrated the significant elevation of total Ig E, CCL5, and CCL11 level in asthma group compared with control group (p < 0.05)." (PMID 33013383, 2020). "Due to the pathological role of eosinophils in asthma and atopic dermatitis, the first studies evaluated the cellular sources of eotaxin-1/CCL11 in the lung and the skin, reporting that epithelial cells, fibroblasts, smooth muscle cells can produce it." (PMID 29962972, 2018). "The levels of eosinophil activators CCL11 and IL-5 were significantly increased in plasma of humanized asthma control group, and CCL11 restored to normal level upon IL-37b administration (all P < 0.05)." (PMID 29988381, 2018). "CCL11 (also known as extaxin-1) plays a pivotal role in recruitment of eosinophils into airways in asthma." (PMID 29138487, 2017). "The chemokine CCL11, also known as eotaxin-1, was first identified in the peripheral immune system as a potent eosinophil chemoattractant in allergic inflammation, asthma, atopic dermatitis, and inflammatory bowel disease." (PMID 28950005, 2017). "The adjusted ORs (95%CI) of abnormal expressions of elevated IL-17A, decreased adipsin and CCL11 for adult asthma patients were 12.50 (5.52, 28.34), 19.55 (11.74, 32.55), and 4.13 (1.78, 9.55) in comparison with normal level, respectively." (PMID 29138487, 2017). "Conversely, some clinical studies indicated that plasma CCL11 expression was higher in asthma attack, uncontrolled and severe asthmatic patients than that in health controls." (PMID 29138487, 2017).
asthma (continued). "During asthma progression, eosinophils are infiltrated into the airway in response to eosinophil chemotactic factors such as CCL11, 24 and 26, which are secreted by airway epithelial cells." (PMID 27010397, 2016). "Prior studies have reported an increase in CCL11 levels in BAL fluids in subjects with asthma after allergen challenge, and CCL11positive cells or CCL11 mRNA expression in bronchial biopsy specimens in asthma." (PMID 26011707, 2015). "We identified that TSLP and CCL11/eotaxin-1 levels were not only significantly elevated in the group with rhinovirus-induced asthma exacerbation, but that their levels had a linear correlation independently of age, gender and ethnicity." (PMID 25546419, 2014). "Some highly significant genes in the microarray analysis also relevant to asthma (Ccl2, Ccl11, Ccl24 and Cxcl5) were further confirmed by quantitative PCR." (PMID 25318534, 2014). "Lastly, we conducted a clinical study in asthmatic children to examine if rhinovirus-induced asthma exacerbations are in fact associated with in vivo airway secretion of TSLP and CCL11/eotaxin-1." (PMID 25546419, 2014). "The C-C chemokine CCL11 is a potent chemoattractant for eosinophils and is thought to play an important role in the pathogenesis of asthma by inducing eosinophil infiltration into the airways." (PMID 23936192, 2013). "It has been described that eosinophils are the main responders to CCL11 at inflammatory sites in asthma, but also in neuromyelitis optica." (PMID 22815714, 2012). "The qRT-PCR analysis of these samples verified results for Ccl8 and indicated a down-regulation of 10 other asthma-related genes (Arg1, Ccl11, Ccl24, Ear11, Mcpt1, Sprr2a, Chi3l3, Chi3l4, Chia, Slc7a2) in EOO versus AOO mice." (PMID 18087596, 2007). "CCL11 was downregulated in media with a high concentration of n-3 LCPUFA and no vitamin D, whereas it was upregulated in media with a high concentration of n-3 LCPUFA and low vitamin D. Elevated levels of CCL11 were commonly observed in patients with asthma, allergic rhinitis, and atopic dermatitis." (PMID 41149648, 2025). "For instance, cytokine CCL11 was initially investigated in the context of asthma and tumors." (PMID 39990233, 2025). "In asthma (particularly T2-high severe asthma), eosinophils are actively recruited to airway tissues in response to chemokines upregulated by IL-4 and IL-13 such as eotaxin-1 (CCL11), eotaxin-2 (CCL24), and eotaxin-3 (CCL26), which binds to CCR3 receptors on eosinophils." (PMID 40004192, 2025). "The serum levels of TNF‐α (p = 0.025), IFN‐γ (p = 0.011), CCL22 (p = 0.022), IL‐12p70 (p = 0.021), CXCL10 (p = 0.028), CCL2 (p = 0.028), CCL13 (p = 0.024), IL‐4 (p = 0.026), IL‐13 (p = 0.024), and CCL11 (p = 0.028) were found to be downregulated in stable asthma when compared to acute asthma." (PMID 39508721, 2024). "Understanding the role of CCL11 on senescence development may have important implications for the treatment of age-related lung diseases, such as asthma." (PMID 37860000, 2023). "Moreover, our study further explores the role of CCL11 as a pro-aging factor in the context of asthma, as evidenced by decreased VEGF expression in AEC of asthmatic patients." (PMID 37860000, 2023). "Furthermore, our results showed an upregulation of NOX1 expression in AEC from children with asthma, which directly correlates with the increased levels of CCL11." (PMID 37860000, 2023). "Furthermore, expression of genes whose expression correlates with asthma, including Il9, Il4, Il13, Ccl11, Ccl24, and Muc5ac, was much lower in recipients of Id1 cKO Th9 cells." (PMID 37867222, 2023). "Seven hypermethylated (CCL11, TNF, IL5, CCL2, CXCL1, CCL8, IL17RB) mRNAs (>twofold compared with control) were finally selected, as their mRNAs have been clearly reported as being associated with asthma." (PMID 36250525, 2022).
asthma (continued). "Eotaxins are increased in the airways of subjects with asthma, and we have previously shown that neutralizing antibodies against eotaxin-1/CCL11 and eotxin-2/CCL24 reduces the number of infiltrating eosinophils in the BALF of OVA-sensitized and challenged mice." (PMID 33946872, 2021). "Immune cells produce indeed a subset of chemokines, especially the cytokine CCL11 which is abundantly produced in the lungs of patients with asthma and also widely expressed in other human tissues including heart, colon, kidney, small intestine, pancreas, liver, and ovaries." (PMID 33608009, 2021). "Indeed, we confirmed the elevated expression of CCL5 and CCL11 in BALF samples from OVA-induced asthma model." (PMID 33013383, 2020). "The Der p-induced asthma model was associated with increased AHR and bronchial wall thickening, elevated serum IL-19, IL-13, IgE levels, BALF IgA levels, increased immune cell infiltration, and tissue IL-33 and CCL11 in the lungs." (PMID 31114590, 2019). "Indeed, there have been early phase clinical trials with CCR3 antagonists for asthma and, more recently, a therapeutic antibody against eotaxin-1/CCL11 (Bertilimumab) for allergic rhinitis." (PMID 29962972, 2018). "For example, eotaxin-1/CCL11 has been used as a biomarker in clinical trials in asthma." (PMID 29962972, 2018). "Eotaxin-1/CCL11 is a chemokine originally implicated in the selective recruitment of eosinophils into inflammatory sites during allergic reactions, being thoroughly investigated in asthma, allergic rhinitis, and other eosinophil-related conditions." (PMID 29962972, 2018). "In plasma samples, CCL11 levels are associated with asthma severity and are not significantly affected by corticosteroid treatment." (PMID 28848734, 2017). "Eotaxin-1 (CCL11), which measured in this study is a potent chemoattractant for eosinophils and has been suggested as a therapeutic target as well as biomarker in various allergic diseases including asthma." (PMID 27283431, 2016). "In addition, we provide new evidence of the in parallel airway secretion of TSLP/CCL11/eotaxin-1 during rhinovirus-induced asthma exacerbations in children." (PMID 25546419, 2014). "In addition, in bronchial biopsies of asthmatic patients, CCL11 expression correlated with asthma severity." (PMID 23606796, 2013). "A recent study showed that IL-35 can reduce airway eosinophilia through the inhibition of eosinophil-attracting chemokines (CCL24 and CCL11) and concluded that IL-35 could be a treatment option for reducing the recruitment of eosinophils into tissues in disorders such as asthma." (PMID 39597537, 2024). "Additionally, CCL11 promotes proliferation and increased collagen expression in lung fibroblasts, suggesting its role in extracellular matrix deposition and tissue remodeling in asthma mediated by fibroblasts." (PMID 37860000, 2023). "Interestingly, a positive correlation exists between these inflammatory markers and CCL11, implying the potential role of eotaxin-1 as a mediator of the pro-inflammatory milieu observed within the lungs of individuals with asthma." (PMID 37860000, 2023). "In addition, Ccl11, Ccl24, and Muc5ac, which correlate with asthma, decreased in Id1 cKO mice." (PMID 37867222, 2023). "However, the siRNA-mediated knockdown of Ob-R receptors in these cells suppresses the leptin-mediated upregulation of IL-6, CCL11, and IP-10, indicating that leptin can play a detrimental role in promoting inflammation in asthma patients by stimulating fibroblast differentiation." (PMID 35888038, 2022). "This was accompanied by reduced levels of CXCL1, CCL11, and CCL2 chemokines and the consequent reduced inflammation in lungs and airways which contributed to the improvement of pulmonary mechanics, the main cause of asthma complications and worsening of life quality of patients with asthma." (PMID 33123138, 2020).